AMER3 (APC membrane recruitment protein 3)
Description:
Regulator of the canonical Wnt signaling pathway. Acts by specifically binding phosphatidylinositol 4,5-bisphosphate (PtdIns(4,5)P2), translocating to the cell membrane (By similarity).
Synonyms: FAM123C; FLJ38377
Tractability: Antibody: UniProt places it where antibodies can reach, with medium confidence; its Gene Ontology location is reachable by antibodies, with medium confidence.
Gene: Protein-coding gene on chromosome 2 (130,755,540 to 130,768,134, forward strand). Ensembl gene ENSG00000178171.
Subcellular location: Cell membrane
Subcellular location (Human Protein Atlas): Nuclear bodies; Cytosol; Nucleoplasm
Gene Ontology:
Molecular function: protein binding; beta-catenin binding; phosphatidylinositol-4,5-bisphosphate binding
Biological process: regulation of canonical Wnt signaling pathway
Cellular component: nuclear body; plasma membrane
Genetic constraint (gnomAD): Missense variants: 1,197 observed, 1,141.7 expected, observed/expected ratio (o/e) 1.05, 90% interval 1 to 1.1. Synonymous variants: 540 observed, 485.07 expected, observed/expected ratio (o/e) 1.11, 90% interval 1.04 to 1.2.
Homologues: Orthologues: chimpanzee AMER3 (99% identical), dog AMER3 (66% identical), pig AMER3 (60% identical), guinea pig AMER3 (60% identical), mouse Amer3 (59% identical), rat Amer3 (59% identical), tropical clawed frog amer3 (26% identical), zebrafish amer3 (23% identical). Paralogues in human: AMER1 (16% identical), AMER2 (13% identical).
Diseases named in the same sentence as AMER3 in open-access papers:
AMER3 is named in the same sentence as 6 diseases in open-access papers, as found by Europe PMC text mining. Sharing a sentence is not in itself a finding about the gene and the disease. The quoted sentences say what the papers report.
colon adenocarcinoma (1 paper, 2022). "Various potential biomarkers for colon adenocarcinoma initiation and progression and drug targets were identified and discussed, including seven novel markers: ACSL4, ANK2, AMER3, EXOSC1, EXOSC6, GCLM, and TFRC." (PMID 35842572, 2022).
tumor (2 papers, 2017 to 2023). "What is more, AMER3 variants modify the U-shaped association of urinary total hydroxyphenanthrene with fasting plasma glucose, however, the association of this gene and tumor is rarely reported." (PMID 37752559, 2023).
AMER3 also shares sentences with these, for which no sentence is quoted: astrocytoma (1 paper); diabetes (1); glioma (1); type 2 diabetes (1).